CAPN6 (calpain 6)
Description:
Microtubule-stabilizing protein that may be involved in the regulation of microtubule dynamics and cytoskeletal organization. May act as a regulator of RAC1 activity through interaction with ARHGEF2 to control lamellipodial formation and cell mobility. Does not seem to have protease activity as it has lost the active site residues (By similarity).
Synonyms: CalpM; CANPX; CAPNX; DJ914P14.1
Tractability: No criterion of Open Targets' tractability assessment is met for any kind of drug.
Gene: Protein-coding gene on chromosome X (111,245,099 to 111,270,483, reverse strand). Ensembl gene ENSG00000077274.
Subcellular location: Cytoplasm, perinuclear region; Cytoplasm, cytoskeleton, spindle
Subcellular location (Human Protein Atlas): Centriolar satellite; Vesicles
Pathways (Reactome):
Extracellular matrix organization: Degradation of the extracellular matrix
Gene Ontology:
Molecular function: protein binding; calcium-dependent cysteine-type endopeptidase activity; microtubule binding
Biological process: microtubule bundle formation; proteolysis; regulation of cytoskeleton organization
Cellular component: perinuclear region of cytoplasm; spindle microtubule; cytoplasm; microtubule; spindle
Homologues: Orthologues: chimpanzee CAPN6 (99% identical), macaque CAPN6 (99% identical), rabbit CAPN6 (98% identical), pig CAPN6 (98% identical), dog CAPN6 (97% identical), guinea pig CAPN6 (95% identical), mouse Capn6 (95% identical), rat Capn6 (95% identical), tropical clawed frog capn6 (49% identical), Caenorhabditis elegans tra-3 (36% identical), Caenorhabditis elegans clp-1 (27% identical), Caenorhabditis elegans clp-7 (26% identical), and 5 more. Paralogues in human: CAPN5 (46% identical), CAPN8 (30% identical), CAPN2 (30% identical), CAPN3 (30% identical), CAPN9 (29% identical), CAPN11 (29% identical), CAPN1 (29% identical), CAPN12 (28% identical), CAPN14 (26% identical), CAPN10 (26% identical), CAPN13 (23% identical), CAPN7 (19% identical), and 8 more.
Diseases named in the same sentence as CAPN6 in open-access papers:
CAPN6 is named in the same sentence as 30 diseases in open-access papers, as found by Europe PMC text mining. Sharing a sentence is not in itself a finding about the gene and the disease. The quoted sentences say what the papers report.
sarcoma (5 papers, 2019 to 2024). A usually aggressive malignant neoplasm of the soft tissue or bone. "Of note, calpain-6 expression in cells and in sarcoma tissues was associated with that of genes involved in DNA repair." (PMID 36153320, 2022). "Researchers found that calpain-6-expressing cells were tumor-initiating and conferred the property of chemoresistance, suggesting an association between calpain-6 and the malignant characteristics of sarcoma cells." (PMID 31673071, 2019). "Calpain-6, a Calpain family member, has been reported to promote the proliferation and metastasis of sarcoma stem cells by activating YAP." (PMID 38547301, 2024). "The functions of calpain-6 clearly link sarcoma SCs to tumor malignancy and possibly to the metastatic process." (PMID 36153320, 2022). "We also found a strong enrichment in a YAP-dependent mitotic gene signature in calpain-6 expressing soft-tissues sarcomas." (PMID 36153320, 2022). "Together these results highlighted the key functions of the calpain-6/YAP axis during the G2M phase in sarcoma stem cells." (PMID 36153320, 2022). "We identified calpain-6 as a marker of sarcoma SCs and showed that calpain-6–expressing cells are at the top of a cell hierarchy." (PMID 35053522, 2022). "We previously showed that the atypical calpain, calpain-6, is expressed in sarcoma cells with CSC properties such as self-renewal, multipotency, chemoresistance and tumor initiation." (PMID 36153320, 2022). "Calpain-6 promotes autophagy and maintains the tumor-initiating cell population in sarcoma stem cells." (PMID 31799196, 2019). "We previously showed the pro-tumor functions of calpain-6 in sarcoma stem cells." (PMID 36153320, 2022). "Calpain-6 expression is associated with genes of the G2M phase of the cell cycle, supports G2M-related YAP activities and up-regulated genes controlling mitosis in sarcoma stem cells and tissues." (PMID 36153320, 2022). "To determine active and targetable mechanisms that contribute to specific pro-tumor functions of sarcoma stem cells, we used the CSC biomarker calpain-6." (PMID 36153320, 2022). "Calpain-6 may also regulate the Hippo pathway and YAP transcriptional activity by modulating cell-cell interactions in sarcoma SCs because the suppression of calpain-6 with shRNA affected the expression of different genes coding cadherins such as CDH2 and CDH11." (PMID 36153320, 2022).
atherosclerosis (4 papers, 2017 to 2026). A disease characterized by the build-up of fatty material and calcium deposition in the arterial wall resulting in partial or complete occlusion of the arterial lumen. "It was also identified that calpain-6 is implicated in macrophage cholesterol metabolism, often characterized as the central doctrine in atherosclerosis." (PMID 38069105, 2023). "Our previous investigations conducted in murine models of atherosclerosis and atherosclerotic lesions in humans have unveiled the robust expression of calpain-6 in foamy macrophages while remaining undetectable in comparatively milder lesions." (PMID 38069105, 2023). "Regarding atherosclerosis, it is likely that calpain-6 is upregulated in macrophages after cells infiltrate into lesions, whereas it is absent in bone marrow cells." (PMID 29270409, 2017). "Calpain-6 (CAPN6) enhances the phagocytic activity of macrophages by disrupting the exon junction complex (EJC)-driven mRNA splicing, thereby promoting the development of atherosclerosis." (PMID 41614904, 2026). "Within the murine atherosclerosis model, calpain-6 did not exhibit expression in monocytes immediately following their mobilization into the atherosclerotic lesion; rather, its induction occurred within the lesion itself." (PMID 38069105, 2023). "Nevertheless, since calpain-6 contribute to the other atherogenic processes in macrophages such as cellular motility, the pathophysiological importance of this endocytic process in the pathogenesis of atherosclerosis has not been fully determined." (PMID 36105534, 2022). "Considering that calpain-6 is exclusively expressed in macrophages in atherosclerotic lesions, it is interpreted that the pinocytotic incorporation of LDL in lesional macrophages, at least of their calpain-6-mediated portion, may be responsible for the pathogenesis of atherosclerosis." (PMID 36105534, 2022).
liver cancer (2 papers, 2016 to 2023). An epithelial or non-epithelial malignant neoplasm that arises from the liver. "The increased expression level of CAPN6 can promote cell proliferation and play an anti-apoptotic role in cervical cancer and liver cancer cells, which favor tumor progression." (PMID 37296697, 2023). "Our previous study shows that Calpain 6 (CAPN6) expression is regulated by PI3K-Akt in liver cancer through POU2F1 and CAPN6 which promote cell proliferation and inhibit apoptosis of liver cancer cells." (PMID 26375440, 2016). "Analysis of flow cytometry showed that knocking down of POU2F1 induced apoptosis rate of liver cancer cell with CAPN6 overexpression to decrease." (PMID 26375440, 2016). "miR-449a has the influences on liver cancer cell behavior partially by down-regulation of CAPN6 and POU2F1." (PMID 26375440, 2016). "Our data demonstrated that miR-449a inhibited liver cancer progression by targeting both CAPN6 and POU2F1." (PMID 26375440, 2016). "miR-449a was negatively associated with CAPN6 and POU2F1 in liver cancer." (PMID 26375440, 2016). "We have demonstrate previously that POU2F1 regulates CAPN6 expression in liver cancer cells." (PMID 26375440, 2016). "CAPN6 and POU2F1 were positively associated with liver cancer." (PMID 26375440, 2016). "Hoechst staining showed that miR-449a could induce a significant apoptosis including nuclear fragmentation and chromosomal condensation in the liver cancer cells, however, in the cells with miR-449a and CAPN6 or POU2F1 overexpression, the apoptosis was attenuated." (PMID 26375440, 2016). "CAPN6 and POU2F1 protein and mRNA levels decreased in liver cancer cells with miR-449a overexpression using western blot and real time RT-PCR assays." (PMID 26375440, 2016). "The study indicated that miR-449a functions as a tumor inhibitor in liver cancer by decreasing POU2F1 and CAPN6 expression in liver cancer." (PMID 26375440, 2016). "CAPN6 and POU2F1 protein levels were overexpressed in liver cancer tissues compared with the normal ones." (PMID 26375440, 2016). "In our study, we identified that CAPN6 or POU2F1 are targets of miR-449a and there was an inverse correlation between miR-449a and CAPN6 or POU2F1 in liver cancer tissue specimens." (PMID 26375440, 2016). "Endogenous CAPN6 and POU2F1 expression in liver cancer cells with miR-449a overexpression were examined." (PMID 26375440, 2016). "Here, we continue to investigate the regulation of CAPN6 and POU2F1 in liver cancer by miRNAs." (PMID 26375440, 2016). "Next, given the fact that CAPN6 and POU2F1 promotes cell proliferation and induce apoptosis resistance in cancer cells, we want to know whether miR-449a suppresses cell proliferation and apoptosis in liver cancer cells by targeting POU2F1 and CAPN6." (PMID 26375440, 2016).
bone sarcoma (1 paper, 2022). A sarcoma that arises from the bone. "In mouse models of bone sarcoma, most tumor cells expressed calpain-6 during the early steps of tumor out-growth." (PMID 36153320, 2022).
bone tumors (1 paper, 2022). "We previously reported that calpain-6 inhibition in K7M2 osteosarcoma cells suppressed their ability to form bone tumors and develop metastases in mice." (PMID 36153320, 2022). "Moreover, calpain-6 and YAP levels were correlated in a 143B cells-derived bone tumor in mouse and in osteosarcoma lung metastases in patients." (PMID 36153320, 2022).
endometriosis (1 paper, 2013). The growth of functional endometrial tissue in anatomic sites outside the uterine body. "Most importantly, the expression of calpain 6, a non-classical calpain, is increased in leiomyosarcomas, while the expression of calpain 5 is decreased in endometriosis." (PMID 23855590, 2013).
glioma (1 paper, 2021). A benign or malignant brain and spinal cord tumor that arises from glial cells (astrocytes, oligodendrocytes, ependymal cells). "In glioma grade IV, highly activated DEGs included STOM, IGHG4, CXCL13, MMP13, and CAPN6, while highly downregulated DEGs included JAZF1-AS1 and ELDR." (PMID 33948562, 2021).
head and neck squamous cell carcinoma (1 paper, 2019). A squamous cell carcinoma that arises from any of the following anatomic sites: lip and oral cavity, nasal cavity, paranasal sinuses, pharynx, larynx, and salivary glands. "In contrast, expression of calpain-6 was downregulated in head and neck squamous cell carcinoma (HNSCC), and decreased expression of calpain-6 was associated with tumorigenesis and poor prognosis in HNSCC, suggesting that calpain-6 could function as a tumor suppressor protein in HNSCC45." (PMID 31673071, 2019).
limb-girdle muscular dystrophy type 2A (1 paper, 2013). "In addition, Capn6 is reported to be overexpressed in the skeletal muscle of patients with limb-girdle muscular dystrophy type 2A (LGMD2A), which is caused by pathological mutations of CAPN3." (PMID 23935533, 2013).
metastatic tumor (1 paper, 2022). "We reveal a novel axis involving calpain-6 and YAP that is activated in CSCs during the early steps of primary and metastatic tumor outgrowth." (PMID 36153320, 2022).
muscular dystrophies (1 paper, 2013). "How the physiological role of CAPN6 in skeletal muscle development is related to the pathological condition of muscular dystrophy, where skeletal muscles are in a continuous cycle of degeneration and regeneration, is an intriguing question." (PMID 23935533, 2013). "In this respect, CAPN6 could be a therapeutic target for muscular dystrophies, since its downregulation is expected to enhance the de novo formation of functional skeletal muscles." (PMID 23935533, 2013). "Our findings indicate that calpain-6 might serve as a therapeutic target for muscular dystrophy/atrophy or as a useful tool in tissue engineering." (PMID 23935533, 2013).
osteosarcoma (1 paper, 2022). A usually aggressive malignant bone-forming mesenchymal neoplasm, predominantly affecting adolescents and young adults. "In contrast, calpain-6 overexpression was associated with higher TEAD transcriptional activity (GT11c) in different osteosarcoma cell lines." (PMID 36153320, 2022). "Here, we use an osteosarcoma cell model, osteosarcoma tissues and transcriptomic data from human tumors to study gene patterns associated with calpain-6 expression or suppression." (PMID 36153320, 2022). "The metastatic model consisting of IC injection of osteosarcoma cells indicates that calpain-6 expressing cells are also involved during the early stages of metastasis outgrowth." (PMID 36153320, 2022). "Because we previously showed that calpain-6 inhibition suppressed the tumor-initiating properties of osteosarcoma cells, we compared transcriptomes of cells that express or overexpress calpain-6 with those of calpain-6 knockdown cells." (PMID 36153320, 2022). "Only part of the cell population expresses calpain-6 in osteosarcoma cell lines." (PMID 36153320, 2022). "Therefore, we used the 143B human osteosarcoma cell line that was modified to express GFP under control of the CAPN6 regulatory sequence to sort and enrich a CSC population expressing basal levels of calpain-6 (Calp6-P-GFP + cells)." (PMID 36153320, 2022). "Calpain-6 could prevent apoptosis in uterine sarcoma and hypoxia-dependent senescence in osteosarcoma cells." (PMID 36153320, 2022). "We previously showed that chemoresistance in osteosarcomas is related to calpain-6 expression." (PMID 36153320, 2022). "Here, we report that calpain-6 and YAP expression are correlated in osteosarcoma cells and tissues." (PMID 36153320, 2022).
Parkinson disease (1 paper, 2013). A progressive degenerative disorder of the central nervous system characterized by loss of dopamine producing neurons in the substantia nigra and the presence of Lewy bodies in the substantia nigra and locus coeruleus. "In addition to our previous study showing the overexpression of the Calpain 6 gene in the medulla oblongata of terminal scrapie, other members of the calpain family have been associated with prion diseases and other neuropathological events, contributing to Alzheimer’s and Parkinson’s." (PMID 23497022, 2013). "Our results suggest that Calpain 6 may be a potential therapeutic target in prion diseases as they are in Parkinson’s disease." (PMID 23497022, 2013). "The other markers (i.e., CAPN6, COL1A2, COL3A1, GALA1 and MTNR1B) belong to gene families with a known role in other neurodegenerative diseases, such as Alzheimer’s or Parkinson’s disease in humans." (PMID 23497022, 2013).
prion disease (1 paper, 2013). A transmissible disease that is caused by a protein that is able to induce abnormal folding of normal cellular proteins, leading to characteristic spongiform brain changes, which are associated with neuronal loss without an inflammatory response. "In conclusion, this study of gene transcription and protein expression and distribution confirm CAPN6, GALA1, MTNR1B and MT2A as potential targets for further prion disease research." (PMID 23497022, 2013).
scrapie (1 paper, 2013). A fatal disease of the nervous system in sheep and goats, characterized by pruritus, debility, and locomotor incoordination. "Further attention should be given to the involvement of calpain 6 in the pathogenesis of scrapie because the neuropil immunostaining was increased in clinical scrapie animals, particularly in the dorsal horn of the spinal cord." (PMID 23497022, 2013). "In agreement with the gene transcription results, a tendency for increased calpain 6 protein immunolabeling and immunoblotting was observed in the majority of the regions analyzed in scrapie-infected animals, being particularly significant in the cSc and Cc of clinical cases." (PMID 23497022, 2013). "The gene and protein expression profiles and protein distribution of six potential genetic biomarkers (i.e., CAPN6, COL1A2, COL3A1, GALA1, MT2A and MTNR1B) are presented here for both the early and terminal stages of scrapie in five different brain regions." (PMID 23497022, 2013). "The increased expression of CAPN6, GALA1 and MT2A in most of the brain regions analyzed suggests a potential role of these genes in early and terminal scrapie pathogenesis, which is further supported by immunohistochemical and immunoblotting evidence." (PMID 23497022, 2013).
Uterine leiomyoma (1 paper, 2020). The presence of a leiomyoma of the uterus. "CAPN6 is also involved in the proliferation and apoptosis of uterine leiomyoma cells and plays a regulatory role in the development of the nervous system of rats." (PMID 32719712, 2020).
uterine tumors (1 paper, 2010). "In addition, Calpain 6 (Capn6) expression was found increased in some uterine tumors." (PMID 20421977, 2010).